KRAS (KRas proto-oncogene, GTPase)
Diseases named in the same sentence as KRAS in open-access papers (continued):
Sharing a sentence is not in itself a finding about the gene and the disease.
non-small cell lung carcinoma (continued). "Of the classic non-small-cell lung cancer oncogenic driver mutations, only two were detected in two patients, a KRAS G12D in a stage IIIA patient (P27) and an ERBB2 gene amplification in a stage IVA patient (P06)." (PMID 31659278, 2020). "KRAS-mutated human non-small cell lung cancers are associated with increased nuclear YAP1, and downregulation of YAP1 has been shown to synergize with the chemotherapeutic agent, cisplatin." (PMID 30956771, 2019). "The comparison of KRAS G12C and G12V with WT KRAS in a panel of 67 non-small cell lung cancer cell lines showed that these mutations decreased AKT activation compared to WT KRAS." (PMID 31681616, 2019). "Previous studies indicate that loss of autophagy inhibits KRAS–triggered tumorigenesis of non small-cell lung cancer." (PMID 30849993, 2019). "Mutated KRAS oncogene in exhaled breath condensate (EBC) can be a genetic marker of non-small cell lung cancer (NSCLC)." (PMID 30368666, 2019). "Adenomatous polyposis coli (APC) and KRAS proto-oncogene (KRAS) mutations frequently co-occur in non-small cell lung cancer." (PMID 31372243, 2019). "In a study, Rizzo and colleagues investigated the association between conventional CT features and EGFR, ALK, KRAS mutations in non-small cell lung cancer." (PMID 30547844, 2018). "The most frequently mutated oncogenes in non-small cell lung cancer (NSCLC) encode the small GTPase KRAS and the epidermal growth factor receptor (EGFR)." (PMID 30590030, 2018). "Of note, CDK4 inhibition was shown to be synthetically lethal with KRAS mutations in non-small cell lung cancer (NSCLC), an observation yet to be explored for PDAC." (PMID 30340359, 2018). "The JUNIPER study is of particular interest since it investigates the effects of abemaciclib on KRAS-mutated non-small cell lung cancer." (PMID 30340359, 2018). "Despite KRAS mutations were identified in Non Small Cell Lung Cancers (NSCLCs) more than 20 years ago, selective and specific inhibitors aimed at directly abrogating KRAS activity are not yet available." (PMID 29464099, 2018). "This study investigated the relationship between epidermal growth factor receptor (EGFR) and Kirsten rat sarcoma viral oncogene homolog (KRAS) mutations in non-small-cell lung cancer (NSCLC) and quantitative FDG-PET/CT parameters including tumor heterogeneity." (PMID 28881771, 2017). "Molecular analysis of the mutation status for EGFR and KRAS are now routine in the management of non-small cell lung cancer." (PMID 28139704, 2017). "Systematic investigation of non-small cell lung cancer cell lines revealed that KRAS mutation can paradoxically increase the sensitivity of cells to cytotoxic agents." (PMID 28152508, 2017). "Such as the KRAS-LCS (rs61764370) polymorphism had been proved to influence the KRAS transcription, resulting in an increased KRAS expression in non-small cell lung cancer." (PMID 28099923, 2017). "Kirsten rat sarcoma viral oncogene (KRAS) mutation is one of the major driver genes of non-small cell lung cancer (NSCLC)." (PMID 27215453, 2016). "Oncogenic mutations in KRAS are detected in upwards of a quarter of non-small cell lung cancers (NSCLC), and are associated with resistance to EGFR inhibitors and potentially also other chemotherapeutics." (PMID 27285753, 2016). "To improve the clinical utility of cfDNA, we developed a sensitive peptide nucleic acid (PNA)-based method for analyzing EGFR and KRAS mutations in the plasma cfDNA of patients with advanced non-small cell lung cancer (NSCLC)." (PMID 27519791, 2016). "In particular, the miRNA let-7 has been suggested to regulate the expression of the KRAS gene, a common mutated gene in non-small cell lung cancer (NSCLC), through a let-7 complementary site (LCS) in 3′UTR of KRAS mRNA." (PMID 26573509, 2015).
non-small cell lung carcinoma (continued). "The aim of this study is to elucidate the significance of EGFR and KRAS mutation in fine needle aspiration (FNA) cytology suspension specimens of non-small cell lung carcinoma." (PMID 25936883, 2015). "The KRAS mutation remains the most common driver mutation in patients with non-small cell lung cancer (NSCLC) and confers a poor prognosis." (PMID 26668062, 2015). "Mutations in epidermal growth factor receptor (EGFR) and KRAS are important markers in non-small cell lung cancer, which are closely related to the clinical therapeutic effect." (PMID 26582224, 2015). "A recent phase II clinical trial (NCT00890825) compared the efficacy of selumetinib in combination with docetaxel versus docetaxel alone in pre-treated patients with KRAS mutation-positive locally advanced or metastatic non small cell lung cancer." (PMID 24956168, 2014). "KRAS mutations are present in 20–30% of non-small cell lung carcinoma (NSCLC) and occur most commonly in adenocarcinoma histology and life-long smokers." (PMID 24782938, 2014). "Non-small cell lung cancers (NSCLCs) that harbor an oncogenic KRAS mutation are often associated with resistance to targeted therapies." (PMID 25245423, 2014). "Kraegel and coworkers analysed KRAS activation in a subset of canine non-small cell lung cancers: despite the wide disparity in the incidence of non-small cell lung cancer between dogs and humans, the frequency of KRAS point mutation was similar." (PMID 24454858, 2014). "The same group also identified the KRAS variant to be associated with 2.3-fold increased risk for non-small-cell lung cancer (NSCLC) among moderate smokers." (PMID 22436609, 2012). "This study is aimed at evaluating the potential of a biochip assay to sensitively detect KRAS mutation in DNA from non-small cell lung cancer (NSCLC) tissue samples." (PMID 22272089, 2011). "In non-small cell lung cancer, the relationship between KRAS mutation and response to EGFR inhibitors is less clear." (PMID 20591134, 2010). "For example, a SNP within the let-7 binding site of the KRAS 3'UTR increases the risk of non-small cell lung cancer by reducing let-7-mediated repression of KRAS." (PMID 19664273, 2009). "Activating RAS mutations, including KRAS, are the most frequent oncogenic mutations present in human tumors, detected in about 20% of non-small-cell lung cancer (NSCLC), 40% of CRC and over 90% of PAC." (PMID 19826477, 2009). "In non-small cell lung cancer, KRAS mutations have been shown to identify a group of patients that do not respond to EGFR targeted therapies and the identification of these mutations is thus clinically important." (PMID 17184525, 2006). "We then screened for KRAS mutations in 30 non-small cell lung cancer biopsies that had been previously sequenced for mutations in EGFR exons 18–21." (PMID 17184525, 2006). "KRAS mutations are frequent oncogenic drivers in non-small cell lung cancer (NSCLC)." (PMID 41919149, 2026). "KRAS G12C inhibitors (G12Cis) have revolutionized the treatment of cancers driven by this historically undruggable mutation, offering unprecedented clinical responses in non-small cell lung cancer (NSCLC) and other malignancies." (PMID 41541668, 2026). "Furthermore, while agents like sotorasib have been approved for KRAS G12C-mutated non-small-cell lung cancer, their efficacy in KRAS-mutated MOC remains under investigation." (PMID 40427025, 2025). "In conclusion, our study indicates that KRAS mutations may serve as a potential positive predictive biomarker in patients with advanced non-small-cell lung cancer treated with immune checkpoint inhibitor monotherapy." (PMID 40558308, 2025). "This meta-analysis investigates whether KRAS mutations can predict better outcomes in patients with advanced non-small-cell lung cancer (NSCLC) treated with immune checkpoint inhibitors (ICIs)." (PMID 40558308, 2025). "KRAS mutations are prevalent in brain metastases (BM) from non-small cell lung cancer (NSCLC)." (PMID 40317086, 2025).
non-small cell lung carcinoma (continued). "Recent advancements have allowed the development of targeted therapeutics for specific KRAS mutations – for example, Sotorasib and the potential Adagrasib for KRAS G12C mutation, currently with applicability in non-small cell lung cancer harboring KRAS G12C mutation." (PMID 39403527, 2024). "In this work, we comprehensively analyzed RAS gene mutations’ molecular background, mutation testing, KRAS inhibitors’ effectiveness with an emphasis on non-small cell lung cancer, the impact of KRAS mutations on immunotherapy outcomes, and drug resistance problems." (PMID 38397927, 2024). "Moreover, several other clinical trials have shown that WEE1 inhibitors, in combination with other agents, are effective against pancreatic cancer, non-small-cell lung cancer, and leukemia with KRAS mutations." (PMID 39335109, 2024). "Importantly, recent research revealed that inhibition of CERK increases VDAC-mediated mitochondrial membrane potential and generates cellular ROS in non-small cell lung cancer with KRAS mutations." (PMID 38556546, 2024). "Additionally, higher mRNA expression of GLS has been detected in KRAS-mutated non-small cell lung cancer (NSCLC)." (PMID 38459595, 2024). "KRAS mutations are involved in several cancers such as colorectal, pancreatic, non-small cell lung cancers, oesophageal adenocarcinoma/gastroesophageal junction cancer, invasive ductal carcinoma, stomach adenocarcinoma, and undifferentiated endometrial carcinoma." (PMID 38938409, 2024). "KRAS mutation is one of the most common oncogenic drivers in non-small cell lung cancer." (PMID 39594840, 2024). "Moreover, YAP signaling was linked to chemoresistance to KRAS G12C inhibitors in non-small cell lung cancer." (PMID 39594817, 2024). "Furthermore, we aimed to explore the prevalence and the clinical and laboratory characteristics of defined KRAS co-mutational groups, as well as their prognostic impact in patients with operable non-small cell lung cancer (NSCLC)." (PMID 38791897, 2024). "on non-small cell lung cancer with the KRAS G12V mutation reported that the use of VS-6766 and Defactinib, a FAK inhibitor, could show synergistic antitumor activity." (PMID 40231011, 2024). "Interestingly, LKB1 loss in KRAS-mutant non-small cell lung cancers (NSCLC) was also associated with epigenetic silencing of STING expression, which promoted cell survival by mediating tolerance of cytoplasmic DNA accumulation." (PMID 37079538, 2023). "However, the KRYSTAL-1 clinical trial has evaluated the usefulness of adagrasib in 116 patients with metastatic non-small cell lung cancer in 116 patients with the KRAS G12C mutation, practically all of whom had received chemotherapy and immunotherapy." (PMID 36836402, 2023). "Also, Zhu and Tian found the radiosensitization effect and mechanism of novel benzothiadiazole derivatives in KRAS-mutated (KRASm) non-small cell lung cancer (NSCLC)." (PMID 37899758, 2023). "The KRAS G12C mutation is common in non-small cell lung cancer (NSCLC)." (PMID 36951997, 2023). "We identified 103 patients with metastatic non-small cell lung cancer harboring KRAS mutations from June 2013 to June 2020, n = 47 KRAS G12C, n = 52 KRAS non-G12C, n = 4 unknown." (PMID 37916173, 2023). "The clinical utility of LP has been demonstrated for the detection of epidermal growth factor receptor (EGFR) mutations in non-small cell lung cancer (NSCLC) patients or for the detection of KRAS proto-oncogene, GTPase (KRAS) mutations in patients suffering from metastatic colorectal cancer (CRC)." (PMID 35328301, 2022).
non-small cell lung carcinoma (continued). "Among them, Amgen’s sotorasib (AMG510) was approved by the FDA in May 2021 for patients with KRAS G12C-mutated non-small cell lung cancer and is the first KRAS-targeted drug marketed worldwide." (PMID 36582783, 2022). "Non-small cell lung cancer (NSCLC) patients with Kirsten rat sarcoma viral oncogene homolog (KRAS) mutation are associated with significant clinical heterogeneity and a poor prognosis to standard NSCLC therapies such as surgical resection, radiotherapy, chemotherapies, and targeted medicines." (PMID 35582540, 2022). "Although its efficacy in PDAC remains unknown, sotorasib, which targets the KRAS G12C mutation, has been developed and has shown anticancer activity in patients with KRAS-G12C-mutated non-small-cell lung cancers." (PMID 35328306, 2022). "Sotorasib (21, brand name Lumakras®) is a Rat Sarcoma (RAS) GTPase family inhibitor developed by Amgen for the treatment of solid tumors with Kirsten Rat Sarcoma Viral Oncogene Homolog (KRAS) mutations, including non-small cell lung cancer (NSCLC) and colorectal cancer." (PMID 35268744, 2022). "Among them, Amgen's sotorasib(AMG510) was approved by the US Food and Drug Administration(FDA) in May 2021 for non-small cell lung cancer patients with KRAS G12C mutation, becoming the first KRAS-targeted drug hitting the world market." (PMID 36118526, 2022). "In this retrospective study including 580 patients with metastatic (Stage IV) non-small cell lung cancer, we investigated whether KRAS mutational status had any impact on clinical outcome." (PMID 35565194, 2022). "KRASG12C is the most commonly mutated variant of KRAS in non-small cell lung cancer." (PMID 35456940, 2022). "However, in non-small cell lung cancer (NSCLC) with KRAS mutation and LKB1 deletion, the expression of carbamoyl phosphate synthase (CPS) 1 increases; this change leads to an increase in the CP, which moves from mitochondria to the cytoplasm." (PMID 33926551, 2021). "Since KRAS harbors the oncogenic mutation G12V in approximately 30% of pancreatic ductal adeno carcinoma and 20% of the colon and non-small cell lung cancers, we used the algorithm ProtAG for theoretical prediction of spliced peptides delineated from the KRASG12V2-35 protein sequence." (PMID 33875134, 2021). "The role of KRAS mutation status in other types of tumors has also been studied, e.g., KRAS mutation is a poor prognostic factor and erlotinib or gefitinib resistance biomarker in non-small cell lung cancer." (PMID 31952366, 2020). "KRAS represents the most commonly mutated oncogene in Caucasian non-small-cell lung cancer (NSCLC)." (PMID 32376889, 2020). "KRAS mutations are found in approximately one third of non-small cell lung cancer (NSCLC) patients." (PMID 33233668, 2020). "Even with a relatively common mutation (e.g. KRAS mutation in non-small cell lung cancer) it is challenging to partition the available cell lines into distinct discovery and validation sets while maintaining statistical power to identify potential dependencies." (PMID 32463358, 2020). "The role of ctDNA is now well established in the clinical decision in certain alterations and tumors, such as the epidermal growth factor receptor (EGFR) mutation in non-small cell lung cancer and the v-Ki-ras2 kirsten rat sarcoma viral oncogene homolog (KRAS) mutation in colorectal cancer." (PMID 32010431, 2020). "KRAS mutations occur in approximately 15-30% of non-small cell lung cancers (NSCLCs)." (PMID 30167080, 2018). "In addition, in human non-small cell lung cancer A549 cells with KRAS mutation, trametinib-mediated elevation of phosphorylated Akt was suppressed by fluvastatin, and the co-treatment of both resulted in the increase of the sub-G1 population." (PMID 29731968, 2018).
non-small cell lung carcinoma (continued). "Somatic point substitution mutations in the KRAS proto-oncogene primarily affect codons 12/13 where glycine is converted into other amino acids, and are highly prevalent in pancreatic, colorectal, and non-small cell lung cancers." (PMID 30042874, 2018). "Furthermore, four tumours harboured KRAS somatic mutations that have been previously shown to have a tendency toward mutual exclusivity with RASSF1a promoter methylation in colorectal and non-small cell lung cancers." (PMID 28194229, 2017). "Targeted delivery of siRNA to undruggable KRAS mutated non-small cell lung cancer cells would sensitize the cells to TKI drugs and offers an efficient therapy for treating cancer; however, efficient delivery of siRNA and releasing it in cytoplasm remains a major challenge." (PMID 27530552, 2016). "By sequencing the regions of the 3′ UTR of KRAS in multiple non-small cell lung cancer (NSCLC) cases, rs61764370 (also known as the KRAS-variant) was identified as the first single nucleotide polymorphism (SNP) within a let-7 complementary site to be a biomarker for NSCLC risk." (PMID 25433809, 2014). "Mutations (EGFR, KRAS, etc) are common in non-small cell lung cancer (NSCLC)." (PMID 24205245, 2013). "In fact, KRAS mutations are present up to 30% in non-small cell lung cancers (NSCLC)." (PMID 23384026, 2013). "Similarly, a SNP in a let-7 miRNA binding site in the KRAS 3′UTR increases Non-Small Cell Lung Cancer risk." (PMID 23555973, 2013). "For example, EGFR and KRAS mutations are reported to be mutually exclusive in non-small cell lung carcinoma, which means that genes selected by their correlation with EGFR mutation status may be not regulated by EGFR, but instead regulated by KRAS." (PMID 19517027, 2008). "Nine of the 30 non-small cell lung cancer biopsies had KRAS mutations detected by HRM analysis." (PMID 17184525, 2006). "Mutations in SMARCA4 have been shown to co-exist with KRAS mutations but are mutually exclusive from common targetable non-small cell lung carcinoma (NSCLC) oncogenes, including EGFR, ALK, MET, ROS-1, and RET." (PMID 40406754, 2025). "Moreover, developing targeted drugs for other point mutations within the KRAS gene is at a bottleneck, with approximately 70% of KRAS-mutant Non-small cell lung cancer (NSCLC) patients with non-G12C point mutations still lacking available therapeutic inhibitors." (PMID 41184283, 2025). "Remarkably, the first approval of targeted therapy for non-small cell lung carcinoma (NSCLC) patients with KRAS mutation has shed light on the development of KRAS-targeting drugs." (PMID 40725120, 2025). "Thus, mutated (m) KRAS represents a cancer driver oncoprotein, and KRAS codon 12 mutations are frequently found in pancreatic ductal adenocarcinomas (PDACs), colorectal adenocarcinomas (CRCs), and non-small-cell lung cancers (NSCLCs)." (PMID 40794198, 2025). "In addition to common EGFR activation mutations, targets such as ALK rearrangement, ROS1 rearrangement, RET rearrangement, BRAF V600E, MET exon 14 skip mutation, KRAS G12C, etc. have been gradually approved for targeted drug application in advanced non-small cell lung cancer." (PMID 38023198, 2023). "In addition, activating KRAS mutations in non-small cell lung cancer (NSCLC), pancreatic and intestinal cancers enhance serine synthesis by increasing transcription of NRF2, a master regulator that promotes serine/glycine synthesis enzyme gene expression through ATF4 activation." (PMID 36932191, 2023). "Recently, G12C mutation gained considerable interest after the FDA approved the use of sotorasib, a KRAS-G12C protein inhibitor, in metastatic non-small cell lung carcinoma (NSCLC) with G12C mutation." (PMID 36899966, 2023).